NOXO1 (NADPH oxidase organizer 1)
Description:
Constitutively potentiates the superoxide-generating activity of NOX1 and NOX3 and is required for the biogenesis of otoconia/otolith, which are crystalline structures of the inner ear involved in the perception of gravity. Isoform 3 is more potent than isoform 1 in activating NOX3. Together with NOXA1, may also substitute to NCF1/p47phox and NCF2/p67phox in supporting the phagocyte NOX2/gp91phox superoxide-generating activity.
Synonyms: P41NOX; SH3PXD5; P41NOXA; P41NOXB; P41NOXC; SNX28
Tractability: Antibody: UniProt places it where antibodies can reach, with high confidence; its Gene Ontology location is reachable by antibodies, with high confidence.
Gene: Protein-coding gene on chromosome 16 (1,978,912 to 1,984,636, reverse strand). Ensembl gene ENSG00000196408.
Subcellular location: Cell membrane (Isoform 3)
Pathways (Reactome):
Signal Transduction: RAC1 GTPase cycle; RAC3 GTPase cycle; RHO GTPases Activate NADPH Oxidases
Disease: WNT5:FZD7-mediated leishmania damping
Gene Ontology:
Molecular function: enzyme binding; protein binding; phospholipid binding; superoxide-generating NADPH oxidase activator activity; phosphatidylinositol binding
Biological process: extracellular matrix disassembly; regulation of hydrogen peroxide metabolic process; regulation of respiratory burst; superoxide anion generation
Cellular component: NADPH oxidase complex; plasma membrane; cytoplasm
Genetic constraint (gnomAD): Loss-of-function variants: 39 observed, 30.14 expected, observed/expected ratio (o/e) 1.29, 90% interval 1 to 1.68. The synonymous counts are far from expectation, so gnomAD's model fits this gene poorly and the ratio says little. Missense variants: 675 observed, 452.84 expected, observed/expected ratio (o/e) 1.49, 90% interval 1.4 to 1.59. Synonymous variants: 302 observed, 203.8 expected, observed/expected ratio (o/e) 1.48, 90% interval 1.35 to 1.63.
Homologues: Orthologues: chimpanzee NOXO1 (99% identical), macaque NOXO1 (91% identical), pig NOXO1 (70% identical), dog NOXO1 (69% identical), rat Noxo1 (65% identical), mouse Noxo1 (64% identical), guinea pig NOXO1 (62% identical), tropical clawed frog noxo1 (34% identical), tropical clawed frog noxo1.2 (33% identical), zebrafish noxo1b (33% identical), zebrafish noxo1a (30% identical). Paralogues in human: NCF1 (22% identical), SH3PXD2A (21% identical), SH3PXD2B (19% identical).